GSN (gelsolin)
Diseases named in the same sentence as GSN in open-access papers (continued):
Sharing a sentence is not in itself a finding about the gene and the disease.
cancer (continued). "The actin-binding protein, gelsolin, is a well known regulator of cancer cell invasion." (PMID 27391159, 2016). "Our finding makes it tempting to speculate a critical role of gelsolin in proteolysis at the invasive front of cancer cells." (PMID 27391159, 2016). "In this study, the TGF-β1-induced MDA-MB231breast cancer cells as a model for CSC differentiation were used to investigate whether the expression level of GSN is regulated by the TGF-β1 signaling for promoting breast CSC differentiation." (PMID 26482896, 2015). "Further dissection of the mechanisms by which gelsolin and other cytoskeletal proteins regulate invasive pathways could contribute towards the understanding of how cancer progresses, and the development of effective strategies which counteract its spread." (PMID 22927998, 2012). "This includes actin-binding protein gelsolin a protein involved in cell motility and required for cancer cell invasion, matrix metalloproteases MMP9 which degrade extracellular matrix and promotes invasion, metastasis-associated proteins S100A4/metastasin and cathepsin B (data not shown)." (PMID 19753117, 2009). "The introduction of gelsolin into various cancers might possibly serve as an antitumour gene therapy in the future." (PMID 12592377, 2003). "GSN is widely found in plasma and cytoplasm and acts as a transcriptional cofactor in signal transduction, and epigenetic changes affect its expression and activity and are essential for various diseases, including cancer, infection and inflammation, and heart damage." (PMID 37035750, 2023). "In OV, it has been reported that the OS and PFS of GSN-positive patients were significantly lower than GSN-negative patients, which may be because high GSN expression conferred chemical resistance to cancer cells by altering GSN-FLICE-like inhibitory protein (FLIP)-Itch interaction." (PMID 37035750, 2023). "In addition, in many cancers, gelsolin expression is increased." (PMID 32992584, 2020). "As CCT binds to gelsolin and possibly acts as a sequesterer for the Ca2+-bound active form, this interaction may be relevant for the effects of gelsolin on cancer progression." (PMID 30506376, 2019). "However, gelsolin can be epigenetically down-regulated in some cancers." (PMID 30506376, 2019). "Thus it appeared that the secreted gelsolin-related death of CD8+ T cells was cancer cell-specific and could be executed during cell contact." (PMID 29100377, 2017). "In this context, our work points out the possibility that GSN could be a key factor in this cell behavior and that its physical association with E7 could increase cell movements, migration and invasiveness in HPV-related cancers." (PMID 27072581, 2016). "Although gelsolin may modulate phospholipid signaling pathways through its high affinity to polyphosphoinositides, the mechanism that restored gelsolin expression suppresses tumorigenicity in cancer cells is not well understood." (PMID 12592377, 2003). "Gelsolin and actin interactions with VDAC1 influence mitochondrial function, energy homeostasis, and apoptosis—which are critical in diseases like cancer and neurodegeneration, where VDAC plays a crucial role in regulating cell survival and death." (PMID 41006687, 2025). "Gelsolin (GSN), an actin binding protein, functions as a switch to control epithelial-mesenchymal transition (EMT) in cancer." (PMID 38175202, 2024). "Therefore, it is likely that gelsolin may play a dual role in cancer genesis." (PMID 39061201, 2024). "In some cancers, the CNV status of GSN was positively correlated with GSN expression and was an adverse factor affecting patient outcomes." (PMID 37035750, 2023). "In tumors with elevated GSN expression, including KIRC, the increase in GSN expression was more significant in early cancers." (PMID 37035750, 2023). "Gelsolin (GSN) is a Ca2+ regulated actin filament, and it impacts on cancer apoptosis and inflammation." (PMID 36291348, 2022).
cancer (continued). "Secreted gelsolin inhibits Clec9a-dependent cross presentation of antigen and dampens CD8+ T cell responses in a cancer model in mice." (PMID 35173718, 2022). "When taken together, the identification of GSN and PRDX4 proteins associated with LNM in CRC may not only be used as novel biomarkers for the early prognosis of CRC metastasis but also act as promising targets for the treatment of cancer growth, migration, and invasion." (PMID 35804959, 2022). "In LNM stage IV of CRC, deregulated GSN and PRDX4 proteins are involved in cancer cell growth and movement, especially invasion and migration." (PMID 35804959, 2022). "It is notable that over-expression of Gelsolin gene in MCF7 and MDA-DB-468 cell lines decrease cancer cells migration and metastasis while its knockdown had reverse impact." (PMID 32636728, 2020). "Thus, the role of gelsolin may differ depending on the cell type or stage of cancer." (PMID 30506376, 2019). "In different cancer cell types, NME1 could bind to gelsolin, thereby inhibiting the actin depolymerizing function of gelsolin and decreasing cell migration." (PMID 39063217, 2024). "Although GSN has been described by others to be highly expressed in chemoresistant cancer cells, our data using patient tissue did not confirm this." (PMID 37046833, 2023). "Specific interactions between SNAREs and Munc18c, gelsolin, supervillin, as well as other unidentified SNARE regulatory proteins, represent potential targets to combat metastasis in patients with invadopodia-forming cancer subtypes." (PMID 34094984, 2021). "In the grade 3 carcinoma, PSD4 and GSN had the higher betweenness (BC = 1.0; BC = 0.193548)." (PMID 32640634, 2020). "GSN, HTRA1, and PDLIM5 were the prognostic genes in the grade 3 carcinoma." (PMID 32640634, 2020). "NEFH also associated with APC (another WNT pathway member, upstream of CTNNB1), through GSN, in our dataset analysis, Thus, these findings might implicate NEFH in WNT signaling in cancer, even as NEFH’s role in cancer is yet to be discovered." (PMID 31740709, 2019). "HDACIs also resulted in cell cycle arrest and growth inhibition by transcriptional activation of other cell cycle regulatory genes such as p16, p27, cyclin E and gelsolin, while inhibition of cyclins A, B1, D1 and D2 were also noted in many cancer cell lines." (PMID 26502922, 2015). "Previously, we showed that secreted gelsolin (sGSN), an extracellular protein that circulates in plasma and is secreted by tumor cells, severs F-actin and blocks DNGR-1 ligand binding, dampening anti-cancer immunity and the efficacy of immunogenic anti-cancer therapies." (PMID 38662827, 2024). "Moreover, regarding the GSN gene, it has been revealed that in healthy colon tissue, the gene GSN and its co-expressed genes participate in KEGG pathways such as 'adherens junction', 'proteoglycans in cancer', 'tight junction', and 'focal adhesion'." (PMID 37365287, 2023). "GSN expression was not consistent throughout the cancer sites." (PMID 37958747, 2023). "Our results suggest that radiation-induced increases of FN1, CTSD, GSN, and MRC2 may play radioresistant and negative roles in cancer therapy." (PMID 26056562, 2015).
infection (22 papers, 2008 to 2025). The state of being infected such as from the introduction of a foreign agent such as serum, vaccine, antigenic substance or organism. "The inhibition of GSN by PKR limits pathogen entry into cells, indicating a role for GSN in the susceptibility of cells to infection." (PMID 34571790, 2021). "In light of these reports, we evaluate here the predictive and therapeutic potential of plasma gelsolin in infections and infection-associated diseases." (PMID 30149613, 2018). "Remarkably, efficient HIV-1 Env-mediated membrane fusion and infection of permissive lymphocytes were impaired when gelsolin was either overexpressed or silenced, which led to a loss or gain of cortical actin, respectively." (PMID 23575248, 2013). "At 72 h post infection, the transcript levels of gelsolin (gsn) were elevated (1.5 and 1.2-fold, p < 0.0001) in the 8 °C and 6 °C groups, respectively, relative to the control group." (PMID 39560796, 2024). "For example, the phosphorylation level of Rho GTPase activating protein was upregulated at 6 h after infection, and actin-depolymerizing factor, focal adhesion kinase 1, and Gelsolin were only upregulated at 36 h after infection." (PMID 38759153, 2024). "Simultaneously, by monitoring the BLI channel we demonstrated that dynamic bacterial-derived fluorescence intensity was limited in gelsolin-treated mice, which indicates decreased infection followed by bacterial eradication (group 6)." (PMID 32272559, 2020). "Efficient HIV-1 fusion, entry and infection is therefore sensitive to the expression of gelsolin and its actin-severing activity." (PMID 23575248, 2013). "Since HIV-1 Env-gp120-induced reorganization of cortical actin has been proposed to be fundamental to promote efficient HIV-1 viral entry and infection, we therefore examined the effect of gelsolin overexpression on HIV-1 entry and infection." (PMID 23575248, 2013). "Actin reorganization is most prominent between 10 to 16 hours post infection and depends on the actin severing and capping protein, gelsolin." (PMID 22238609, 2012). "This strongly suggests that gelsolin is essential for efficient egress of progeny virions during MVM infection." (PMID 18704167, 2008). "We show here that in MVM-infected cells, gelsolin accumulates not only along rigid actin fibers but also at the plasma membrane and, at a later stage of infection, within actin patches." (PMID 18704167, 2008). "Gelsolin was found to colocalize with phalloidin-stained actin structures whatever the infection status and time." (PMID 18704167, 2008). "Decreased plasma CRTAC1 could result from decreased production as occurs with ALB and TTR, increased turnover as occurs during severe infection with GSN serving as a scavenger for filamentous actin being released from cells, or a combination of mechanisms." (PMID 37667413, 2023). "Additionally, infection with L. amazonensis or L. braziliensis led to reduced RhoA and gelsolin expression in BMDM." (PMID 37576604, 2023). "Interestingly, three sRNA genes in the L8 transgenic tobaccos were identified, corresponding to an abortive infection protein, a cytidylyltransferase, and a terpene synthase; and one in the L1 tobaccos matched with a gelsolin." (PMID 33477999, 2021). "In addition, the following were observed in cats after infection with T. gondii: malate dehydrogenase, serotransferrin, keratin, phosphoglycerate mutase, elongation factor, ceruloplasmin, gelsolin, crystalline alpha chain and annexin A1." (PMID 34906132, 2021). "In the context of cytoskeleton dynamics, actin adaptors and enzymes that reorganize, stabilize and sever cortical F-actin, such as MSN (moesin), FLNA (filamin A), and GSN (gelsolin) have been involved in early infection, and are responsible for pore fusion and viral entry." (PMID 33995324, 2021). "Our study found the altered expression of Gelsolin (GSN) during sub-clinical infection." (PMID 32518370, 2020).
infection (continued). "Further studies will be necessary to explore this hypothesis, and to elucidate the role of gelsolin in conditions of cell activation and infection." (PMID 23575248, 2013). "Moreover, silencing endogenous gelsolin expression negatively affected HIV-1 entry and infection in function of the degree to which endogenous gelsolin was silenced." (PMID 23575248, 2013). "This hypothesis was validated by analyzing the effects of gelsolin overexpression or specific knockdown on early infection with endocytotic VSV-G pseudotyped viral particles." (PMID 23575248, 2013). "Although direct effects of gelsolin on bacterial growth have not been observed so far, a few studies suggest the beneficial role of GSN in modulation of the host antimicrobial response, thus providing the possibility that gelsolin may be a sensitive infection biomarker and therapeutic tool." (PMID 30149613, 2018). "Moreover, it is plausible that the action of other actin cytoskeleton-associated cellular components may be crucial for early HIV-1 entry and infection, as proposed here for gelsolin." (PMID 23575248, 2013). "We show that gelsolin-induced modulation of actin filaments is essential to virus egress and provides strong evidence that progeny virions move to the cell periphery through vesicular transport and start to be released into the medium before cell collapse at the end of infection." (PMID 18704167, 2008). "Furthermore, gelsolin/actin colocalization was strongly reduced upon MVM infection." (PMID 18704167, 2008). "Additionally, genes related to cell adhesion such as ADGRF5, CAVIN2, FAT3, FILIP1, GSN, and TSPAN11 were downregulated in both the variants at 24hpi whereas CAV1, CAVIN1, GPC3, POSTN, SUSD2, and TSPAN7 were downregulated only after Delta variant infection at 24 hpi." (PMID 41200555, 2025). "Only three proteins (GSN, PLEC, and STRIP1) and one transcript (MYOM3) related to the cytoskeleton organization and dynamics were regulated in the lower trachea after infection with huH1N1." (PMID 39247193, 2024). "The use of gelsolin:GFP and Sep5:GFP to follow actin reorganization has helped to understand cytoskeleton dynamics during infection-related development." (PMID 28742127, 2017). "Gelsolin is an actin adaptor with filament-severing activity, and overexpressing and silencing gelsolin have been shown to impair efficient HIV fusion and infection due to disruption of cortical actin." (PMID 29085362, 2017). "Identifying such signals will also help further characterize the role of gelsolin in HIV-1 fusion, entry and infection of CD4+ T lymphocytes in vivo." (PMID 23575248, 2013). "The degree of gelsolin silencing is correlated with the extent to which HIV-1 entry and infection, and HIV-1 Env-induced cell-to-cell fusion were blocked in these cells." (PMID 23575248, 2013). "Both these processes appear to be influenced by actin-severing gelsolin, suggesting that alteration of gelsolin activity or expression can restrict HIV-1 entry and infection." (PMID 23575248, 2013). "Both these processes appear to be influenced by actin-severing gelsolin, suggesting that gelsolin activity can restrict HIV-1 entry and infection." (PMID 23575248, 2013). "To explore the roles of gelsolin and its F-actin severing activity in early HIV-1 entry and infection, we used a C-terminal enhanced green fluorescent protein (EGFP)-tagged wild type gelsolin (gelsolin-EGFP) derived from the permissive CEM.NKR-CCR5 T cell line." (PMID 23575248, 2013). "Therefore, both overexpression of functional gelsolin or specific knockdown of endogenous gelsolin negatively affects HIV-1 Env-mediated actin dynamics, entry and infection at a pre-fusion step." (PMID 23575248, 2013). "Taken together, our data suggest that the actin-severing activity of gelsolin is fundamental for HIV-1 to influence cortical actin dynamics, and to appropriately adjust the amounts of actin available for reorganization during viral fusion, entry and infection." (PMID 23575248, 2013).
infection (continued). "The functional role of gelsolin-mediated actin severing during HIV-1 fusion and infection was further demonstrated in HIV-1 Env-mediated membrane fusion models and in infected permissive lymphocytes in which endogenous gelsolin expression had been silenced by specific RNA interference." (PMID 23575248, 2013). "Our findings suggest that by severing cortical F-actin, gelsolin regulates actin dynamics, the amount of F-actin available for reorganization, lymphocyte plasma membrane morphology, and viral receptor capping during HIV-1 viral entry and infection." (PMID 23575248, 2013). "Therefore, it appears that gelsolin silencing specifically affects HIV-1 Env-mediated viral entry and infection." (PMID 23575248, 2013). "We found that overexpression of functional intracellular gelsolin or specific silencing of endogenous gelsolin expression restricts HIV-1 entry and infection by altering the amounts of cortical F-actin, and by perturbing F-actin dynamics and the associated changes in pseudopodium morphology." (PMID 23575248, 2013). "Neither the efficiency of infection nor the levels of the different viral DNA forms appeared to be altered by the presence of gelsolin-neutralizing antibodies." (PMID 18704167, 2008). "Microglial actins in astrocyte-co-cultures were down-regulated after HIV-1/VSV infection and the proteins related to actin binding, polymerization and stability, including MARCKS, moesin, Wiskott-Aldrich syndrome protein (WAS) and gelsolin, were all up-regulated." (PMID 18575609, 2008). "Accordingly, endogenous gelsolin may act as a limiting factor for early HIV-1 entry and infection." (PMID 23575248, 2013). "In this case, gelsolin activity appeared essential to either the formation or the release of infectious progeny virions, since cells exposed to infection-1 culture supernatants showed markedly lower levels of MVM DNA when the infection-1 cells had been treated with αGln (Inf2)." (PMID 18704167, 2008). "Accordingly, cells in which endogenous gelsolin expression is reduced or absent are refractory to HIV-1 Env-mediated membrane fusion, viral entry and infection due to impairment of these multiple F-actin-driven events." (PMID 23575248, 2013). "Accordingly, cells in which endogenous gelsolin is absent or reduced are refractory to HIV-1 entry and infection, due to alterations in these F-actin-dependent events." (PMID 23575248, 2013). "Together, these observations suggest that overexpression of functional gelsolin restricts HIV-1 entry and infection of permissive lymphocytes regardless of viral tropism." (PMID 23575248, 2013). "The entry and infection of VSV-G pseudotyped viral particles, using equal viral inputs for these virions that for X4- and R5-tropic HIV-1 strains, were not affected by the specific silencing of endogenous gelsolin using siRNA1-GSN or siRNA2-GSN oligos." (PMID 23575248, 2013). "Entry and infection of these pseudotyped viral particles, using equal viral inputs for these virions and that for X4- and R5-tropic HIV-1 strains, were not significantly affected by gelsolin overexpression." (PMID 23575248, 2013).
cardiovascular diseases (9 papers, 2013 to 2025). "For example, Gelsolin (GSN, P06396) associates with cardiovascular disease with a hazard ratio of 0.6, P = 4.9 × 10-10 and demonstrates a Pearson r of 0.21 with its paired measured protein." (PMID 41361833, 2025). "We found that miR-21 was able to suppress GSN, an important transcriptional cofactor in signal transduction in cardiovascular diseases." (PMID 30180843, 2018). "During the past 5 years, many scholars began to focus on gelsolin's possible role in the development of cardiovascular diseases." (PMID 23533533, 2013). "Gelsolin has previously been identified as a prognostic factor in various cardiovascular diseases." (PMID 40106086, 2025). "Coagulation is an ongoing process in serum and deficiencies of several proteins, such as protein Z (PROZ), fibronectin 1 (FN1), and gelsolin (GSN), have been identified to be involved in cerebrovascular and cardiovascular diseases." (PMID 27379006, 2016).
neurodegenerative disease (8 papers, 2010 to 2025). A disorder of the central nervous system characterized by gradual and progressive loss of neural tissue and neurologic function. "The decrease of GSN concentration in blood and CSF of MS subjects indicates the involvement of this protein in the process of neurodegenerative disease development." (PMID 21040581, 2010).
metabolic disorders (3 papers, 2019 to 2025). "The restoration of GSN expression, therefore, suggests a potential therapeutic approach for mitigating liver injury in metabolic disorders such as MASH." (PMID 40390546, 2025).